RAC3 (Rac family small GTPase 3)
Diseases named in the same sentence as RAC3 in open-access papers (continued):
Sharing a sentence is not in itself a finding about the gene and the disease.
brain malformations (2 papers, 2023 to 2024). "Pathogenic variants in RAC3 cause a neurodevelopmental disorder with brain malformations and craniofacial dysmorphism, called NEDBAF." (PMID 38214746, 2024).
chronic myelogenous leukemia (2 papers, 2018 to 2024). "RAC3 was over-expressed in human chronic myeloid leukemia K562 cells, which are normally resistant to TRAIL-induced apoptosis." (PMID 38200409, 2024). "It is worth noting, however, that Rac3 was initially identified in a chronic myelogenous leukemia (CML) cell line." (PMID 30558116, 2018).
cognitive deficits (2 papers, 2016 to 2019). "Thus we conclude that both hyper- and hypoactivation of Rac1/Rac3 have similar consequences on migration, neuritogenesis and synaptogenesis, and impacts on the maturation of the inhibitory network causing similar cognitive deficits." (PMID 27713499, 2016).
endothelial dysfunction (2 papers, 2021 to 2022). In vascular diseases, endothelial dysfunction is a systemic pathological state of the endothelium (the inner lining of blood vessels) and can be broadly defined as an imbalance between vasodilating and vasoconstricting substances produced by (or acting on) the endothelium. "The results indicated the role of RAC3 on endothelial dysfunction by down-regulating autophagy." (PMID 35410298, 2022). "Moreover, Rac3 modifies the induction of endothelial dysfunction by oxidized low-density lipoprotein in human umbilical vein endothelial cells." (PMID 33011741, 2021).
gastric cancer (2 papers, 2021 to 2023). A primary or metastatic malignant neoplasm involving the stomach. "Many recent studies have reported the expression patterns and biological effects of RAC3 in various tumours, such as oesophageal, breast, bladder and gastric cancer." (PMID 37386813, 2023). "Many studies have reported the expression and function of Rac3 in cancers, such as esophageal, breast and gastric cancer." (PMID 34257551, 2021).
glioma (2 papers, 2015 to 2022). A benign or malignant brain and spinal cord tumor that arises from glial cells (astrocytes, oligodendrocytes, ependymal cells). "This includes effects on cell invasion (RAC1, RAC2, RAC3, RHOA, RHOC), focal adhesion formation (RHOA), stemness of glioma precursor cells (RAC1), cell proliferation (RAC1, RND3) and cell cycle (RND3)." (PMID 26132659, 2015). "Seven Rho GTPases (RND1, RND3, RAC3, RHOA, RAC2, RAC1 and RHOC) showed a significantly greater connectivity in grade IV glioma and seven (CHP, RHOD, RHOF, RHOB, RHOQ, RND2, RHOBTB3) showed greater connectivity in grade II glioma." (PMID 26132659, 2015).
HIV-1 infection (2 papers, 2024 to 2025). The type species of lentivirus and the etiologic agent of acquired immunodeficiency syndrome (AIDS). "Although omitted from downstream analyses, the Rac3 NLS protein behaved similar to the C-MYC protein in HIV-1 infection assays." (PMID 38979149, 2024).
leukaemia (2 papers, 2019 to 2021). "While Rac1 regulated the chemotactic response of ALL cells to chemokine SDF-1α (CXCL12) produced by stromal cells, molecular inhibition of Rac3 prolonged the survival of mice with BCR/ABL induced leukaemia." (PMID 34679751, 2021). "Conversely, BCR/ABL transgenic mice express activated Rac3 in primary precursor B lymphoblasts, with molecular inhibition of Rac3 increasing survival of mice harbouring BCR/ABL+ leukaemia." (PMID 34679751, 2021). "Interestingly, crossing of Bcr/Abl transgenic mice with Rac3 knockout mice has shown that the lack of Rac3 is associated with longer survival of the transgenic animals, indicating a stimulatory role for Rac3 in leukemia in vivo." (PMID 31514269, 2019).
lymphoma (2 papers, 2010 to 2021). A malignant (clonal) proliferation of B- lymphocytes or T- lymphocytes which involves the lymph nodes, bone marrow and/or extranodal sites. "Analytical results indicated that some inferred genes, such as RAC3, TEC, IRAK2/3/4, PRKCE, SMAD3, BLK, TXK, PRKCQ, were associated with the initiation and progression of lymphoma." (PMID 34899868, 2021). "Early in 2006, researchers from France confirmed that the absence of RAC3 can trigger the initiation and progression of B-cell lymphoma, reflecting the potential association between RAC3 and lymphoma." (PMID 34899868, 2021). "Studies of Rac3-null mice indicate that Rac3 but not Rac1 or Rac2 specifically contributes to the development of Brc/Abl-induced lymphomas in vivo." (PMID 20822528, 2010). "The analytical results showed that some of these genes (RAC3, TEC, IRAK2/3/4, PRKCE, SMAD3, BLK, TXK, PRKCQ) could be novel lymphoma-associated genes." (PMID 34899868, 2021).
prostate tumor (2 papers, 2011 to 2019). "In the current study we investigate the roles of Rac1, Rac3, and RhoG GTPases in the process of prostate tumor cell diapedesis across a bone marrow endothelial cell layer." (PMID 21776386, 2011). "In the current study, we queried whether Rac3 and RhoG GTPases also have a role in prostate tumor cell diapedesis." (PMID 21776386, 2011). "Rac3 and Rac1 have opposite effects in PC-3 prostate tumor cell diapedesis; while depletion of Rac1 inhibits diapedesis, Rac3 knockdown promotes diapedesis, showing that Rac1 is required for PC-3 cell diapedesis across a bone marrow endothelial cell layer, while Rac3 inhibits tumor cell diapedesis." (PMID 31514269, 2019).
sarcoma (2 papers, 2022 to 2025). A usually aggressive malignant neoplasm of the soft tissue or bone. "Studies have shown that WNT7B, CA9, MMP13, and RAC3 are associated with poor outcomes in sarcomas." (PMID 36428766, 2022).
atherosclerosis (1 paper, 2021). A disease characterized by the build-up of fatty material and calcium deposition in the arterial wall resulting in partial or complete occlusion of the arterial lumen. "Thus, the RAC2/RAC3 network may play a role in atherosclerosis and senescence—pathophysiologic processes that have been implicated in the progress of CVD in TC patients—as well as bleomycin-induced pneumonitis." (PMID 33011741, 2021).
B-cell lymphoma (1 paper, 2021). "The first gene is RAC3 (ENSP00000304283), which had been associated with B-cell lymphoma." (PMID 34899868, 2021).
cervical cancer (1 paper, 2019). A primary or metastatic malignant neoplasm involving the cervix. "This underlines that the functional mechanism of RAC3 in cervical cancer sample maybe need to be further investigated." (PMID 31133010, 2019). "More interestingly, RAC1 as the paralog of RAC3 was reported to play an important role in cervical cancer progression." (PMID 31133010, 2019).
developmental and epileptic encephalopathy 23 (1 paper, 2022). "Dedicator of cytokinesis protein 7 (DOCK7), which is localized to the developing axons, activates Rac1 and Rac3 small GTPases and regulates neuronal polarity; moreover, its variants cause developmental and epileptic encephalopathy 23 (DEE23)." (PMID 36030824, 2022).
diabetes (1 paper, 2013). "Similarly, significant differences in Rho family GTPase signalling, namely, the Rac3 and Cdc42 pathways, which regulate cytoskeletal organisation and membrane trafficking and have been proposed to be linked to diabetes, were among the top ten pathways scored." (PMID 23841104, 2013).
lymph node metastasis (1 paper, 2024). "Elevated RAC3 expression was significantly correlated with an advanced tumor stage, lymph node metastasis, and poor prognosis for BLCA patients." (PMID 39351351, 2024).
lymphoblastic leukemia (1 paper, 2019). "Rac3 is expressed in malignant lymphoblastic leukemia cells; activated Rac3, but not Rac1 or Rac2, can be detected in malignant precursor lymphoblasts from Bcr/Abl transgenic mice." (PMID 31514269, 2019).
Macrocephaly (1 paper, 2021). Occipitofrontal (head) circumference greater than 97th centile compared to appropriate, age matched, sex-matched normal standards. "PAK1 is a common interactor to RAC1 and RAC3, and is associated with an autosomal dominant NDD known as intellectual developmental disorder with macrocephaly, seizures, and speech delay (IDDMSSD, OMIM # 618158)." (PMID 34943902, 2021). "TRIO (OMIM * 601893) is instead a more specific interactor of RAC3 and it is linked to autosomal dominant intellectual disability 44 with microcephaly (OMIM # 617061) or macrocephaly (OMIM # 618825)." (PMID 34943902, 2021).
metastatic cancer (1 paper, 2016). A carcinoma which has spread from the original site of growth to another anatomic site. "The higher concentration of EH not only inhibit Rac1 but also Rac3 and Cdc42 in the MDA-MB-435 metastatic cancer cells." (PMID 26766136, 2016).
metastatic disease (1 paper, 2008). "Subsequently, activation of Rac3 was found to be critical for integrin and growth factor-mediated regulation of cellular migration and adhesion, which are important steps in the progression of metastatic disease." (PMID 18826651, 2008).
otitis media (1 paper, 2021). Inflammation of the anatomical structures of the middle ear, which is most often caused by an infectious process. "Although there is insufficient direct evidence that RAC3 is involved in otitis media, a clinical genomic database (ClinVar Miner) indicates that the Talkowski Laboratory of Massachusetts General Hospital has demonstrated associations of RAC3 variants with otitis media." (PMID 34912812, 2021).
pancreatic adenocarcinoma (1 paper, 2023). "Three genes (MAP2K2, RAC3, and PAK4) that were conserved in the SSCs of all three primates were also involved in numerous pathways, including “Pancreatic adenocarcinoma pathway”, “Integrin-mediated Cell Adhesion”, “Regulation of Actin Cytoskeleton”, and “Ras signaling”." (PMID 36902187, 2023).
cancer (46 papers, 2008 to 2025). A tumor composed of atypical neoplastic, often pleomorphic cells that invade other tissues. "Receptor-associated coactivator 3 (RAC3) is an oncogene that is highly expressed in many malignant tumors and regulates cell cycle progression and cell proliferation, invasion, and migration." (PMID 40906438, 2025). "Stiff 3D culture wasassociated with the downregulation of tumor suppressors (LATS1, BCAR3, CDKN2C), as well as theupregulation of cancer-associated genes (RAC3)." (PMID 38466617, 2024). "Rac3, a member of the p21 Rho family of small GTPases, is an understudied paralog of the canonical Rac1 GTPase and has been implicated in cancer cell proliferation, invasion, and autophagy." (PMID 36555156, 2022). "RAC3 is up-regulated to play an oncogenic role in several cancers, however, the underlying mechanism of RAC3 in BCa is yet to be elucidated." (PMID 33062641, 2020). "In this work we studied the association between RAC3 overexpression on cancer cell stemness and the capacity of this protein to induce cancer stem properties in non tumoral cells." (PMID 29464039, 2018). "In both cancer cell lines, Rac3 siRNA caused a reduction of 75% in Rac3 mRNA and protein levels relative to that seen in cells transfected with a non-targeting control siRNA." (PMID 23388133, 2013). "We found that genes coexpressing with Rac3 were associated with signal transduction, DNA replication, cell proliferation, the cell cycle and pathways in cancer, and we speculate that Rac3 may also be related to these pathways." (PMID 34257551, 2021). "Moreover, previous experimental evidence supports a transforming effect of the three different Rac3 variants identified in this study, which have been all observed in databases of somatic variation in cancer." (PMID 31514269, 2019). "In order to determine if RAC3 overexpression could be mainly associated to one cancer stem cell marker, we first isolated the CD133+ enriched side population from wild type HCT116 cells using a specific antibody conjugated to magnetic beads." (PMID 29464039, 2018). "In addition, independently of the oncogenic profile, is the association of cancer stem markers and properties with RAC3 overexpression, which was supported through our findings analyzing microarrays from tumoral tissues and cell lines." (PMID 29464039, 2018). "Therefore, being RAC3 an oncogene and also a required factor to maintain the stem properties of normal cells, in this work, we investigated its association with cancer stem cell phenotype." (PMID 29464039, 2018). "It was previously demonstrated that both RAC3 or the splicing Delta 4-SRC3 variant downregulation inhibits the oncogenic potential of cancer cells affecting several pathways related to its activity as a coactivator of nuclear receptors or the cytoplasmic signaling." (PMID 29464039, 2018). "Notably, overexpression of RAC3 has been implicated in the development of various cancers." (PMID 39872053, 2024). "In the first case, the increased RAC3 expression could be a heritable marker from the normal stem cell that once mutates to give a cancer stem cell, but in the second, we have to consider the possible signaling inducing this overexpression in mature differentiated cells." (PMID 29464039, 2018). "The experimental results revealed the substantial suppression of cancer cell characteristics such as cell proliferation, migratory patterns, invasiveness, and the ability to form colonies upon RAC3 knockdown." (PMID 39351351, 2024). "This discovery aligns with the established notion that RAC3 functions as an oncogene across a spectrum of human cancers." (PMID 38987564, 2024). "Rac3 is highly expressed in many malignant tumors and is involved in the regulation of tumorigenesis through different mechanisms." (PMID 37728806, 2024). "Current studies have shown that Rac3 is involved in a variety of malignant tumors, including breast, endometrial, and lung cancers." (PMID 37728806, 2024).
cancer (continued). "The rac family of small GTPase 3 (RAC3) functions as an oncogene in various human malignant tumours and plays an important role in tumour development." (PMID 37386813, 2023). "EHop‐016, the RAC1 and RAC3 dual‐target inhibitor, has the potential as an anti‐cancer compound to block cancer progression via multiple Rac‐directed mechanisms." (PMID 37386813, 2023). "We also analyzed the expression of RAC3 in subgroups from different clinical characteristics and found that RAC3 expression progressively increases with cancer progression." (PMID 35847878, 2022). "Rac family of small GTPase 3 (RAC3), one of the Rho GTPase family members, has been reported that overexpression of RAC3 emerged in several cancers." (PMID 35125116, 2022). "KEGG analysis revealed that the genes coexpressed with Rac3 were mainly enriched in the cell cycle, pathways in cancer, Ras signaling and insulin signaling pathways." (PMID 34257551, 2021). "KEGG pathway analysis showed that genes coexpressed with Rac3 were significantly enriched in the cell cycle and pathways in cancer." (PMID 34257551, 2021). "Previous studies indicated that RAC3 promoted cell proliferation and cell aggressiveness in several cancers." (PMID 33062641, 2020). "Recently, research has demonstrated that RAC3 is up-regulated to serve as an oncogene by promoting cell proliferation and cell aggressiveness in several cancers including breast cancer, prostate cancer, brain cancer, and lung cancer." (PMID 33062641, 2020). "Further insight into the cancer-related gene expression unraveled that 22 of DEGs were upregulated by shNrf1, of which 4 genes (i.e., RAC3, PDGFA, GSTA4, and RXRA) were downregulated by Nrf1α−/− (, and )." (PMID 32273945, 2020). "The data presented in this review highlight the emerging roles of the Rac3 GTPase in normal development, and the recent implication in neurodevelopmental human disease, as well as in different types of cancers." (PMID 31514269, 2019). "This review will present the growing experimental evidence that is pointing to important and unique functions of the Rac3 GTPase in neuronal development and cancer." (PMID 31514269, 2019). "Studies have reported that its related pathways, ERK and RAC signaling, are key regulators in leukocyte and cancer cell migration and RAC3 was further proved to regulate cell proliferation, differentiation and migration in several cancers." (PMID 31133010, 2019). "Concerning cancer progression, RAC3 shows to be early overexpressed and maintained at advanced degree of the sickness." (PMID 29464039, 2018). "In turn, RAC3 silencing induced diminished tumoral properties and cancer stem cells as determined by Hoechst efflux, tumorspheres and clonogenic growth, which correlated with decreased Nanog and OCT4 expression." (PMID 29464039, 2018). "RAC3 is a member of the p160 family of steroid receptor coactivators and it is highly expressed in several human cancers, contributing to enhanced cell proliferation and cellular transformation." (PMID 30062065, 2018). "Our results demonstrate that RAC3 is required for maintaining and induction of cancer cell stemness." (PMID 29464039, 2018). "Although the cancer stem cells origin is still unclear, our results demonstrate that the phenotype of cells where RAC3 is overexpressed resembles some characteristics of normal stem cells, like the expression of stem gene markers and growing behaviour." (PMID 29464039, 2018). "Previous studies demonstrated that RAC3 is a critical predictor of cancer prognosis in different cancer types." (PMID 29209153, 2017). "To complete this investigation of the molecular mechanism of Rac3 action in cancer cell aggressivity, we also analyzed the profile of cytokine secretion by MDA-MB-231 cells." (PMID 23388133, 2013). "Inversely, aberrant Rac3 expression and activation, along with the effectiveness of its downstream pathways in cancer cells, contribute to cancer aggressiveness." (PMID 23388133, 2013).